BRCA1 (BRCA1 DNA repair associated)
Diseases named in the same sentence as BRCA1 in open-access papers (continued):
Sharing a sentence is not in itself a finding about the gene and the disease.
breast cancer (continued). "Additionally, olaparib has gained approval from the US FDA for the adjuvant treatment of high‐risk, HER2‐negative breast cancer patients carrying germline BRCA1/2 mutations who have undergone neoadjuvant or adjuvant chemotherapy." (PMID 38895905, 2024). "Furthermore, Swedish national guidelines recommend that RM specimens undergo histopathologic examination for patients aged ≥40 years, except in cases of a family history of breast cancer or the presence of genetic mutations (e.g., BRCA1/2)." (PMID 38451995, 2024). "Other environmental factors may be responsible for the generation of the second mutation; for example, if an individual with one BRCA1 mutation was exposed to radiation, then the radiation could generate the second mutation and breast cancer could occur." (PMID 38339129, 2024). "Approximately 75% of breast cancer patients have mutations or low expression of BRCA1 or BRCA2." (PMID 38244591, 2024). "The existing literature on the influence of physical activity on breast cancer prevention in individuals with BRCA1 and BRCA2 mutations is constrained, thereby highlighting the requirement for more extensive investigations to explore this association in greater detail." (PMID 38715015, 2024). "Breast cancer patients with P/LP variants in BRCA1/2 had, approximately, the same age at diagnosis as patients with P/LP variants in other genes, with average ages at diagnosis of 44.9 years (range from 24 to 77, ±11.6) and 46.7 years (range from 18 to 79, ±6.4)." (PMID 39684352, 2024). "In BRCA1/2 carriers who have been treated for high-grade serous carcinoma of the ovary, fallopian tube, or primary peritoneum, the risk of developing a subsequent breast cancer is lower than reported for unaffected BRCA carriers." (PMID 38248108, 2024). "It is interesting to note that BRCA1 mutations have been linked to skewed XCI in breast cancer." (PMID 38827026, 2024). "It calculates breast cancer risk by considering factors such as age, family history of breast cancer, hormonal factors (e.g., age at menarche and age at first birth), breast density, and the presence of specific genetic mutations (e.g., BRCA1 and BRCA2)." (PMID 38674216, 2024). "Germline mutations related to breast cancer include BRCA1, BRCA2, CHECk2, ATM, PALB2, and PTEN." (PMID 39684874, 2024). "Similarly, the immunogenicity and the response to immunotherapy of breast cancers seem to be different between tumors with a BRCA1 or a BRCA2 mutation." (PMID 39544936, 2024). "Moreover, the cumulative risks of developing breast cancer in male BRCA1 and BRCA2 mutation carriers are 1% and 7–8%, respectively, significantly higher than the 0.1% risk observed in the average male population." (PMID 39590130, 2024). "Due to the diversity of the samples, we were able to interrogate the data relative to several key breast cancer risk modifiers, such as age, parity and BRCA1 or BRCA2 germline mutations, enabling us to uncover cellular interactions and compositional changes associated with each factor." (PMID 38548988, 2024). "However, BRCA1/2 mutation carriers using oral contraceptives showed a heightened risk of breast cancer (HR 1.39, 95% CI 1.15–1.67)." (PMID 39606555, 2024). "Furthermore, a germline mutation in the BRCA1 gene is associated with a higher lifetime risk (72%) for developing breast cancer than for BRCA2 mutation carriers (69%)." (PMID 39011181, 2024). "Patients with breast cancer at a young age were more likely affected by the gene pathogenic variants BRCA1/2 than the general population, and in our study, we observed seventeen patients with BRCA1/2 mutations (13.0%)." (PMID 38999531, 2024). "One study conducted in Argentina that included 155 women with breast cancer, ovarian cancer, and both, with an average age of 42 years (range: 28–81 years), showed a prevalence of 25.8% of BRCA1 and BRCA2 mutations among patients who met the criteria for hereditary ovarian cancer." (PMID 39338246, 2024).
breast cancer (continued). "The mRNA expression of BRCA1 is upregulated in breast cancer tissues harbouring BRCA1 mutation." (PMID 39080120, 2024). "Breast cancer susceptibility genes BRCA1 and BRCA2 encode multifunctional proteins." (PMID 38711004, 2024). "The present study demonstrates that, in addition to the breast cancer patients with germline BRCA1/2 mutation, the patients with wild-type BRCA1/2 who are high-risk of having hereditary breast cancer (BRCAx) also carry an increased risk of CBC recurrence when compared to that of low-risk patients." (PMID 38254240, 2024). "It has been suggested that estrogen may play an important role in the development of breast cancer in carriers of BRCA1 mutations, which is especially pronounced during periods of active cell proliferation and differentiation in the mammary gland." (PMID 38785550, 2024). "Data on HRT and breast cancer risk in BRCA1/2-pV carriers after RRSO is limited." (PMID 39259360, 2024). "Loss or decreased expression of BRCA1 is reported in 30–60% breast cancer tissues." (PMID 38734703, 2024). "Interestingly, it has very recently been described that BRCA1-deficient breast cancer cells are sensitised to TH5487 demonstrating a new synthetic lethal partnership between HR deficiency and OGG1 inhibition." (PMID 38368415, 2024). "However, less than 10% of breast cancer incidence among young women is attributable to heritable mutations in the BRCA1 or BRCA2 genes." (PMID 38790221, 2024). "In the future, patients with advanced breast cancer with BRCA1/2 mutation in China and the United States will be more inclined to choose talazoparib as the first choice of treatment, rather than the traditional Eribulin, capecitabine, gemcitabine, and vinorelbine treatment." (PMID 38886516, 2024). "In breast cancer cells, the breast cancer susceptibility gene BRCA1 and BRCA2 genes are significant tumor suppressors for DNA double-strand breaks (DSBs) by homologous recombination (HR) and their mutation easily causes genetic instability and leads to the emergence of tumor cells." (PMID 38370471, 2024). "A meta-analysis of women with a BRCA1/2 genetic mutation found that preventive salpingo-oophorectomy was associated with a strong reduction in ovarian cancer risk, ranging from 71 to 96%, and a 50% reduction in breast cancer risk." (PMID 39192282, 2024). "Carriers of the BRCA1 or BRCA2 genetic mutation have an 80 to 85% risk of developing breast cancer." (PMID 39335183, 2024). "MPD shares the same risk factors as other breast carcinomas, including advanced age, obesity, alcohol consumption, familial genetic mutations including BRCA1 and BRCA2, prior chest radiation exposure, hormone replacement therapy, prolonged oral contraceptive use, and family history of breast cancer." (PMID 39188449, 2024). "Another possible reason is that BRCA1 mutations may be associated with a higher likelihood of developing bilateral breast cancer, which could increase the risk of disease progression." (PMID 38098088, 2023). "We found that higher young-adult BMI is associated with lower premenopausal breast cancer risk in both BRCA1 and BRCA2 variant carriers in the retrospective analysis, with consistent, although not statistically significant, risk estimates in the prospective analysis." (PMID 37340476, 2023).
breast cancer (continued). "In conclusion, PARP inhibitor combined with platinum-based chemotherapy was proved as the optimal treatment for patients with metastatic, locally advanced, or recurrent breast cancer carrying BRCA1/2 pathogenic variants in terms of efficacy outcomes, namely ORR, PFS, and OS." (PMID 36865806, 2023). "TNBC or ER+ breast cancer patients who are BRCA1-deficient are sensitive to DNA-damaging drugs." (PMID 37298108, 2023). "Additionally, one in three individuals with BRCA1/2 mutations will develop breast cancer by the age of 50." (PMID 37987348, 2023). "Interestingly, the vast majority of breast cancers that occur in BRCA1 mutation carriers have a TNBC phenotype that prevents patients from being treated with therapies targeting hormone receptor pathways." (PMID 37373065, 2023). "Also, previous research revealed that methylation of the BRCA1 promoter in peripheral blood DNA was linked to a 3.5-fold increased risk (95% CI, 1.4–10.5) of developing breast cancer before the age of 40." (PMID 37506102, 2023). "Variables such as the age of menarche and menopause, parity and breastfeeding, hormone replacement therapy usage, additional genetic variants, and lifestyle components like diet and exercise all contribute to shaping the breast cancer risk in individuals with BRCA1 mutations." (PMID 37762577, 2023). "We identified patients with breast cancer harboring BRCA1 or BRCA2 mutations." (PMID 36905492, 2023). "However, obesity enhances other risk factors in premenopausal women, such as a family history of breast cancer or inherited breast cancer 1 or 2 (BRCA1/2) mutations." (PMID 37296891, 2023). "However, other studies reported higher cumulative breast cancer risk (72%) to age 80 for BRCA1 and 69% for BRCA2 carriers." (PMID 37781190, 2023). "However, given that the prevalence of BRCA1/2 mutations is estimated to be 1:400–1:500 in the general population and 1:30–1:40 in the average breast cancer patient, it can be concluded that the vast majority of these patients are BRCA1/2-mutation-negative." (PMID 37623237, 2023). "Additionally, two patients with breast cancer, both carrying BRCA1 mutations (ESCAT IA), received olaparib in later lines." (PMID 38111812, 2023). "In canines, mutations in these genes could also predispose certain breeds to develop mammary tumors, with BRCA1 being more strongly associated with malignant cases in canines." (PMID 37835752, 2023). "Interestingly, although BC and OC are two different cancers that arise in different tissues of the body, women with breast cancer susceptibility gene type 1 and type 2 (BRCA1 and BRCA2) mutations have a higher risk of developing BC and/or OC." (PMID 37445860, 2023). "We studied DDRs in cells from heterozygous ABRAXAS1-mutation carriers to understand whether breast cancer-associated mutations in the gene encoding the BRCA1 complex partner ABRAXAS1 entail similar phenotypic changes as described for BRCA1-mutations." (PMID 37198153, 2023). "We discovered that 5.08% of patients carried pathogenic germline HRR gene mutations, which may increase the risk of developing other cancers, such as BRCA1/2 for breast cancer." (PMID 37387466, 2023). "However, gene screening is costly and BRCA1 or BRCA2 mutations cause only 5% of breast cancer, limiting applicability to the general population." (PMID 37018164, 2023). "One group of investigators in Thailand used the Multiplex Ligation dependent Probe Amplification (MLPA) method to screen for BRCA1/2 large genomic rearrangement in Thai patients with familial breast cancer; they only found BRCA1 alteration in 1% of high‐risk patients with breast cancer." (PMID 35778884, 2023). "It has been proposed that the HIF pathway is integral to the progression of BRCA1-associated breast cancer and may be a target for emerging targeted therapies directed to this pathway and downstream targets." (PMID 36831687, 2023).
breast cancer (continued). "Only in one instance did a breast cancer patient have both BRCA1 and BRCA2 variants." (PMID 37306523, 2023). "However, cell death due to the inability to timely repair DNA double-strand damage occurs in tumor cells with HR repair defects regulated by mutations in breast cancer susceptibility genes 1/2 (BRCA1/2), among others." (PMID 37954854, 2023). "Besides, overexpression of MAD2L1 leads to chromosomal instability in lung tumour cells, and is highly correlated with high levels of BRCA pathway activity and BRCA1/2 pathogenic mutations in breast cancer patients." (PMID 37469408, 2023). "We show why the loss of NORE1A expression in breast cancers may be particularly important for the development of tumors that are BRCA1 deficient and Her2 positive." (PMID 37627161, 2023). "The most common cause of hereditary breast cancer are mutations in the BRCA1 or BRCA2 genes." (PMID 37108398, 2023). "Detecting loss-of-function mutations in HRR genes other than BRCA1/2 may recognize an additional small subgroup of patients with breast cancer susceptible to PARPi therapy." (PMID 37173992, 2023). "However, BRCA1/2 mutations constitute but a small part of breast cancers, approximately 25% of patients with TNBC, which itself is said to constitute about 15% of all breast cancers presented." (PMID 37662839, 2023). "The average risk of developing breast cancer with the BRCA1 mutation at age 70, is 65%." (PMID 37368765, 2023). "Therefore, these have made it imperative for the recurrent and founder mutations of the BRCA1/2 genes within low income countries to be identified and included in breast cancer screening and diagnosis." (PMID 37055759, 2023). "In addition to regulating transcriptional activity, BRCA1 promotes the maturation and differentiation of breast luminal tissue, and impaired differentiation is a phenotype of BRCA1 mutations in breast cancer cells." (PMID 37108225, 2023). "Our findings indicate that BRCA1/2 pathogenic variants may well contribute to breast cancer incidence in Tanzania." (PMID 35908255, 2023). "In addition to BRCA1/2 mutations, high exposure to estrogen also increases the risk of breast cancer." (PMID 37108225, 2023). "Many previous studies have identified Fgfr2 as an oncogene for breast cancer 35, 36, yet its role in BRCA1-associated breast cancer remains unclear." (PMID 37063417, 2023). "Also, we included numerical scores that represent mutation burden, chromosomal instability (CIN), tumor cell growth and proliferation, BRCA1/2 pathogenic mutation status, and genomic alteration statuses of 11 known breast cancer genes." (PMID 37475004, 2023). "However, the primary analysis mixed studies on patients at different disease stages, and no comparative results were provided for patients with advanced breast cancer and BRCA1/2 pathogenic variants." (PMID 36865806, 2023). "Two breast cancer patients (P8 and P16) had the BRCA1 mutation." (PMID 36768623, 2023). "Furthermore, breast cancer patients with BRCA1/BRCA2-deficiency have recently been shown to benefit from PARP inhibitor treatment which is well-known in ovarian cancer, where BRCA1/BRCA2 mutational status is routinely used for directing this treatment." (PMID 37316882, 2023). "Spautin-1 enhances the inhibition of colony formation of BRCA1-deficient mammary tumor cells." (PMID 37887330, 2023). "Moreover, we observed that breast cancer cells with BRCA1 mutation and ZNF251KD (BRCA1mut + ZNF251KD) were not only resistant to various PARPis, but also to platinum-based drugs and DNA polymerase theta (Polθ) inhibitors." (PMID 37066268, 2023). "In our study, BRCA1 PTVs showed weak associations with overall breast cancer risk (p > 0.05)." (PMID 37790698, 2023). "Additionally, in breast cancer with BRCA1 or BRCA2 gene mutations, the amplification percentage of CXCL1 gene is 3.85% (2/52)." (PMID 37108425, 2023).
breast cancer (continued). "In addition to BRCA1/2, other breast cancer risk-causing factors, such as estrogen receptor signaling and reactive oxygen species, can cause the accumulation of R-loops and/or hinder their resolution." (PMID 37108225, 2023). "Although in healthy individuals carrying BRCA1/2, bilateral mastectomy can reduce breast cancer risk, the overall survival for most BRCA1/2 carriers remain unclear (Peleg Hasson, Menes & Sonnenblick, 2020)." (PMID 37426414, 2023). "Hereditary breast cancer is most commonly attributed to germline BRCA1 and BRCA2 gene variants." (PMID 37895014, 2023). "It has been suggested that breast cancer patients with BRCA1/2 mutations may benefit from precision treatments, such as platinum-based chemotherapy and poly ADP-ribose polymerase inhibitors." (PMID 37055759, 2023). "Of the candidate markers for BRCA1 mutant tumors, we discovered and validated one oncogene Mrc2, whose loss could reduce mammary tumor growth in vitro and in vivo." (PMID 37612741, 2023). "Even if the relative risks for anthropometric measures and breast cancer in BRCA1 and BRCA2 variant carriers are similar to those found in the general population, the absolute excess risks will be higher for BRCA1 and BRCA2 variant carriers because of the higher background breast cancer risk." (PMID 37340476, 2023). "Finally, we considered the two studies published so far testing the association between FANCM MVs and breast cancer risk conducted using familial designs and excluding carriers of BRCA1 or BRCA2 pathogenic variants." (PMID 36707629, 2023). "Accumulating evidence suggests that further clinical exploration of PARPi as monotherapy or combinations have shown benefit in patients with BRCA1 or BRCA2 mutation (gBRCAm)-associated breast cancer, as well as in breast cancer with homologous recombination repair (HRR) dysfunction." (PMID 36832085, 2023). "Loss of BRCA1, a mutation of BRCA1, manifested in 45% of hereditary breast cancers was associated with low autophagic activity, leading to an increase in the level of HIF1α and leading to the production of ketone bodies and modulation of the autophagic activity." (PMID 38234683, 2023). "Additionally, we investigated the potential of curcumin to suppress miR-155-5p in BRCA1-deficient breast cancer cell lines." (PMID 37240365, 2023). "Furthermore, biochemical analyses revealed that DDT26 also mildly inhibited PARP1, a critical target for treating breast cancers with BRCA1/2 mutations." (PMID 38099141, 2023). "To test whether BRCA1-mutated ZNF251KD breast cancer cells are sensitive to DNA Polθ inhibitors, we treated MDA-MB-436 WT and ZNF251KD3 cells with Polθ polymerase inhibitors ART-558 and ART-81223 followed by the clonogenic assay." (PMID 37066268, 2023). "Mutations in the BRCA1 lead to malfunctions and increase the risk of breast cancer." (PMID 37112468, 2023). "A study by Sonderstrup of 411 BRCA1/2mut early breast cancers showed that stromal TILs increasing in 10% intervals were significantly associated with OS (Hazard Ratio 0.92, 95% CI 0.84–1.00, p = 0.05) in BRCA1 and BRCA2mut breast cancers." (PMID 36831687, 2023). "Poly (adenosine diphosphate-ribose) polymerase inhibitors (PARPis) have demonstrated antitumor activity in cancers with a homologous recombination deficiency (HRD) and have recently been approved by the FDA for the treatment of germline BRCA1/2-mutation-associated breast cancer." (PMID 37173992, 2023).